CCND1 (cyclin D1)
Diseases named in the same sentence as CCND1 in open-access papers (continued):
Sharing a sentence is not in itself a finding about the gene and the disease.
neuroblastoma (continued). "Additionally, it was also demonstrated that PROX1 strongly inhibits the proliferation of neuroblastoma cell lines as well as cyclin D1, cyclin-A, and cyclin B1, consistent with a role in cell cycle arrest." (PMID 25526434, 2014). "Furthermore, the combined inhibition of the direct identified targets such as CCND1, CHAF1A, INCENP and BCL-XL could reveal new vulnerabilities of high-risk neuroblastoma." (PMID 30770954, 2019). "In neuroblastoma (NB), genomic amplifications of CCND1 and cdk4 were observed in primary tumors, albeit at low frequency." (PMID 26029996, 2015). "In addition, the levels of Cyclin D1 were correlated with YB-1 expression level across the tested neuroblastoma cell lines, suggesting that YB-1 promotes Cyclin D1 expression in neuroblastoma cells." (PMID 25993060, 2015). "Moreover, Cyclin D1 overexpression has been reported to prevent differentiation in neuroblastoma." (PMID 23383150, 2013). "In neuroblastoma, FAM107A forms a complex with F-actin to negatively regulate cell cycle progression through suppressing cyclin D1 expression." (PMID 38188687, 2023). "In neuroblastoma cells, COMMD1 can form a complex with other proteins to inhibit cyclin D1 expression, G1/S transition, and proliferation." (PMID 34493238, 2021). "In a series of neuroblastoma cell lines, GATA3 was found to positively regulate cyclin D1 transcription by directly binding its promoter sequences." (PMID 33803938, 2021). "For example, the expression footprint of six neuroblastoma-related genes (ALK, BIRC5, CCND1, MYCN, NTRK1 and PHOX2B) have been used to differentiate neuroblastoma molecular subtypes." (PMID 34842635, 2021). "COMMD1 causes tumor apoptosis in lung cancer by suppressing SOD1 expression, and in neuroblastoma, elevated nuclear expression of COMMD1 inhibits cyclin D1 expression, G1/S transition, and tumor cell proliferation." (PMID 34493238, 2021). "Several cell cycle regulators, especially those within the cyclin D1/CDK4/CDK6/RB pathway, are hyperactive in neuroblastoma." (PMID 29719597, 2018). "In particular, silencing of CCND1 and PLK1 showed the most pronounced effects in reducing neuroblastoma cellular proliferation." (PMID 26225123, 2015). "Real-time monitoring of cell growth showed that knockdown of CCND1 and PLK1 had the strongest effects in reducing the proliferation of neuroblastoma cells." (PMID 26225123, 2015). "Cyclin D1 maintains cellular proliferation in the vast majority of neuroblastoma tumors, suggesting that GATA3 exerts oncogenic potential by transactivating cyclin D1 in neuroblastomas." (PMID 33803938, 2021). "We found that knock-down of GATA3 decreased CCND1 expression in neuroblastoma cell lines and that in tumour samples, there was high expression of CCND1 compared to FA and a good correlation between GATA3 and CCND1 expression, as found by others." (PMID 31831790, 2019). "Based on these results, we conclude that the observed anti-proliferative effect of miR-193b in neuroblastoma is mediated, at least in part, through targeting both cyclin D1 and MYCN, two oncogenes with essential roles in neuroblastoma tumorigenesis and thereby attractive therapeutic targets." (PMID 29719597, 2018). "Functionally, miR-193b induces a G1 cell cycle arrest and cell death in neuroblastoma cell lines by reducing the expression of MYCN, Cyclin D1 and MCL-1, three important oncogenes in neuroblastoma of which inhibition has shown promising results in preclinical testing." (PMID 29719597, 2018). "In summary, miR-193b overexpression induces a cell cycle arrest and apoptosis in neuroblastoma by reducing the expression of MYCN, cyclin D1 and MCL-1, three important oncogenes in neuroblastoma whose inhibition by inhibitors have shown promising results in preclinical testing." (PMID 29719597, 2018).
neuroblastoma (continued). "In addition, different Snps are present in the 3′UTR of mouse and human CCND1: Snp rs7178, localized on CCND1 3′UTR, is involved in neuroblastoma, and Snp rs7177, localized on CCND1 3′UTR, is involved in cognitive behavior." (PMID 29599703, 2018). "To confirm the effects of the active products on native DYRK1A in a cellular context, we made use of a SH-SY5Y neuroblastoma cell line expressing human DYRK1A and antibodies directed against cyclin D1 phosphorylated at Threonine 286, a reported DYRK1A phosphorylation site." (PMID 29039762, 2017). "Recently, XAV939 has been shown to decrease neuroblastoma cell survival by inhibiting β-catenin transcriptional activity and decreasing expression of cyclin D1 in both MYCN-amplified and non-amplified cell lines." (PMID 25266063, 2015). "Our results showed that knockdown of CCND1 induces a reduction in cellular proliferation in the majority of the neuroblastoma cell lines in comparison to the scrambled siRNA negative control." (PMID 26225123, 2015). "The 11q13 amplicon is generally located at the same chromosome region of the single-copy genes involved (CCND1, etc.); other amplifications, such as those involving MYCN in neuroblastomas, are inserted in several places in the genome other than chromosome 2, where MYCN gene is mapped." (PMID 20540739, 2010). "VPA also inhibited the proliferation of SHSY5Y neuroblastoma (NB) cancer cells in a time- and dose-dependent manner by downregulating URG4/URGCP and its transcriptional target CCND1, leading, in turn, to cell cycle arrest." (PMID 36139561, 2022). "Moreover, growth and therapeutic resistance in neuroblastoma was shown to be mediated through the miR-15a/16-1–ERK and Bcl-2/Cyclin D1 pathways which supports our findings that miR-15a-5p may play a pivotal role in ECD development." (PMID 34785791, 2022). "From our results, we could not interpret precisely why cyclin D1 was not upregulated in neuroblastoma." (PMID 30235818, 2018). "As CCND1 aberrations are known to contribute to neuroblastoma, this might explain why, as opposed to individuals with MYCNThr58Met, individuals with the MAXArg60Gln variant do not have neuroblastoma, despite the overlapping phenotypes and underlying molecular mechanisms." (PMID 38141607, 2024). "We show that treatment of mouse neuroblastoma Neuro-2A cells with Tet34, but not its scrambled control (Tet34s), induced cell proliferation, as manifested by changes in protein levels of transcription factors and progrowth molecules cyclin D1, PCNA, Sox5, and Cdk2." (PMID 36162508, 2022). "Therefore, we could not detect a gradual incline in CCND1 expression by staging of neuroblastoma in the datasets GSE49710 and GSE85047." (PMID 30235818, 2018). "The expression level of pro-proliferative Ki67 and cyclin D1 (CCND1) genes, as well as of MYCN and Nestin (controlling neuroblastoma aggressiveness), did not undergo any significant change in cells, independent of either 2D or 3D condition." (PMID 33230715, 2021). "Cyclin D1 is a sensitive but not specific immunohistochemical marker for CCSK and many other pediatric renal malignant neoplasms as well as for neuroblastoma." (PMID 30736802, 2019). "The mRNA levels of TG2 isoforms, hypoxia-inducible factor (HIF)-1α, p16, cyclin D1 and B1, as well as markers of cell proliferation/death, DNA damage, and cell cycle were examined in SH-SY5Y (non-MYCN-amplified) and IMR-32 (MYCN-amplified) neuroblastoma cells in hypoxia/reoxygenation conditions." (PMID 32085516, 2020).
multiple myeloma (62 papers, 2006 to 2025).
oral squamous cell carcinoma (61 papers, 2006 to 2025). "Further, elevated levels of PCNA and cyclin-D1 have been associated with more aggressive behavior in oral squamous cell carcinoma (OSCC), leading to multidrug resistance and exerting a detrimental effect on the prognosis and overall outcome of patients." (PMID 39124760, 2024). "We performed a comprehensive meta-analysis for evaluation of cyclin D1 overexpression in oral squamous cell carcinoma to determine the strength of this association." (PMID 24675814, 2014). "The present study was carried out to study the immunohistochemical reactivity and expression of cyclin D1 and its association with site, clinical staging, and histopathological differentiation of oral squamous cell carcinoma." (PMID 22629227, 2012). "The association between cyclin D1, clinicopathologic parameters and prognosis in oral cavity squamous cell carcinoma (OSCC) is inconclusive." (PMID 22336657, 2012). "This case control retrospective study was carried out to study the immunohistochemical reactivity and expression of cyclin D1 and its association with site, clinical staging, and histopathological differentiation of oral squamous cell carcinoma (OSCC)." (PMID 22629227, 2012). "However, we observed that higher expression of Jun or CCND1 or SPP1 was associated with short survival of oral squamous cell carcinoma patients." (PMID 30459815, 2018). "Cyclin D1 is important for the development and progression of several cancer types, including that of oral epithelial cancer that occurs by the transformation of the buccal mucosa causing oral squamous cell carcinoma (OSCC)." (PMID 25645517, 2015). "It is interesting to note that also in the most frequent tumor of the oral cavity, the oral squamous cell carcinoma, cyclin D1 is frequently overexpressed which has a strong impact on the patients prognosis." (PMID 33804108, 2021). "The amplification of the well-known oncogenes CCND1 and EGFR was associated with a metastatic lymph node, as shown by the OS and DFS in a previous oral squamous cell carcinoma (OSCC) study in Taiwan." (PMID 34070941, 2021). "Upregulation of CCND1 and CCND3 genes was associated with cisplatin resistance in human oral squamous cell carcinoma cell lines." (PMID 33923996, 2021). "Co-amplification of CTTN, SHANK2 and CCND1 genes has been reported previously in oral squamous cell carcinoma." (PMID 32252688, 2020). "Among these, the cyclin D1 has been deeply investigated and were shown to be essential for the tumorigenesis of melanoma, breast cancer, and colon and oral squamous cell carcinoma (OSCC)." (PMID 31878037, 2019). "We analysed the expression of cyclins A2, B1, D1, and E1 by immunohistochemistry and numerical aberrations in CCND1 gene by fluorescence in situ hybridization technique in 67 primary oral squamous cell carcinomas (OSCC)." (PMID 29785357, 2018). "The aim of the current study was to evaluate the expression of cyclins A2, B1, D1, and E1 and CCND1 gene status in a single cohort of patients with oral squamous cell carcinomas (OSCC) and relate them to clinical-pathologic characteristics and patient outcome." (PMID 29785357, 2018). "Our findings indicated that cyclin D1 expression correlates with detrimental clinicopathological outcome and poor prognosis in oral squamous cell carcinoma." (PMID 24675814, 2014). "Cyclin D1 expression has been studied in various carcinomas including oral squamous cell carcinomas." (PMID 22629227, 2012). "For example, overexpression of cyclin D1 in oral squamous cell carcinomas is twice as frequent as CCND1 amplification." (PMID 16598186, 2006). "Alternatively, as CCND1 amplifications are also most frequently seen in HPV-independent VSCC, it might be worth exploring the potential additive oncogenic effects of EGFR and CCND1 alterations, as recently shown in oral squamous cell carcinomas." (PMID 34209172, 2021). "This same peptide reduced proteins’ expression related to oral squamous cell carcinoma (cyclin D1)." (PMID 34795699, 2021).
oral squamous cell carcinoma (continued). "CCND1 has been discovered to be upregulated in SCCs such as laryngeal squamous cell carcinomas (LSCCs), head and neck squamous cell carcinomas (HNSCCs) and oral squamous cell carcinomas (OSCCs)." (PMID 34068010, 2021). "A previous study has shown that different growth factors or their receptors or transcription factors (e.g., AP-1, NF-κB, and β-catenin) can upregulate the expression of cyclin D1/E proteins and cyclin D1 protein stability/nuclear accumulation in oral squamous cell carcinoma." (PMID 25591548, 2015). "Hence, this retrospective laboratory-based study was undertaken to study the expression of cyclin D1 in oral squamous cell carcinoma and to correlate its expression with histological differentiation." (PMID 22629227, 2012). "Indeed, recurrent coamplification of the cytoskeleton-associated genes CCTN and SHANK2 with the cell-cycle control gene CCND1 has been observed in oral squamous cell carcinoma." (PMID 18268492, 2008). "Furthermore, our preliminary results from 50 oral squamous cell carcinoma samples showed that the inverse expression pattern of CCND1 and CCND3 correlates with cisplatin sensitivity." (PMID 16978399, 2006). "The expression analysis of cyclin D1, Ki-67, MCM3 and MCM2 in oral squamous cell carcinoma to identify biomarkers is of interest." (PMID 38415027, 2023). "Therefore, evaluation of cyclin D1 expression in pre-operative biopsy specimen may be useful in prognosticating and planning most appropriate treatment strategies in patients with tobacco-related oral squamous cell carcinoma." (PMID 21537090, 2011). "A similar correlation has been reported for cell lines from oral squamous cell carcinoma (TPCN2, CCND1, ORAOV1, ANO1, FADD, PPFIA1 and EMS1; FADD, PPFIA1 and EMS1)." (PMID 20664600, 2010). "Likewise, in oral squamous cell carcinoma, BAP18 promotes cell cycle progression and proliferation by activating CCND1 and CCND2 transcription via MLL1 complex recruitment and H3K4me3 enrichment at their promoters." (PMID 40818609, 2025). "Similarly, it was reported that Yap1 formed complex with TEAD4 in the nuclei regulating the transcriptions of G1 arrest-related genes, such as CCND1, CCNE, CDK2, CDK4, and CDK6, in human oral squamous cell carcinomas." (PMID 31455378, 2019). "The clinicopathological significance of cyclin D1 overexpression and prognosis of oral squamous cell carcinoma has not been fully quantified." (PMID 24675814, 2014). "Moreover, curcumin mediated inhibition of Notch1 activation also led to the downregulation of NF-κB and its target genes, including Bcl-2, cyclin D1, vascular endothelial growth factor (VEGF), and matrix metalloproteinase-9 (MMP-9) in oral squamous cell carcinoma cells." (PMID 24024180, 2013).
lymph node metastasis (57 papers, 1998 to 2025). "CCND1 amplification and cyclin D1 overexpression in HNSCCs have been reported to be associated with a high rate of relapse, lymph node metastasis and shorter patient survival." (PMID 34298667, 2021). "Previous studies showed that high expression of nuclear cyclin D1 is associated with lymph node metastases in PTCs." (PMID 30428594, 2018). "Cyclin D1 positive tumors were smaller than 2 cm (55.6%, p = 0.005), had a low incidence of lymph node metastasis (38.2%, p = 0.04) and were associated with increased DFS of >150 months (p = 0.04)." (PMID 20152033, 2010). "The presence of a BRAF mutation and overexpression of the Cyclin D1 protein have been predominantly observed in lymph node metastasis, suggesting that these factors may play an important role in metastasis." (PMID 39407879, 2024). "Moreover, studies showed that overexpression of Cyclin D1 is associated with lymph node metastases (OR 2.26; 95% CI 1.61–3.16)." (PMID 35626215, 2022). "Overexpression of CCND1 was associated with lymph node metastasis." (PMID 22761904, 2012). "However, only the expression levels of the proliferation-related genes Cyclin D1 and Cyclin E1 were significantly associated with the lymph node metastasis, and only the Cyclin E1 and MMP9 expression levels showed significant correlation with distant metastasis (M stage)." (PMID 34975298, 2022). "Cyclin D1: Its expression was more frequent in cases with lymph node metastasis and less commonly observed in gastric-type SBA." (PMID 41008809, 2025). "Other genes showing high fold change were FGF19 (highest 14.4 in a lymph node metastasis sample), CCND1 (highest 14.3 in a lymph node metastasis samples), and EGFR (highest 11,0 in a tumor sample)." (PMID 39324009, 2024). "Early studies have found that the expression of Cyclin D1 is related to the degree of differentiation of papillary thyroid carcinoma, its invasive biological behavior and the presence of lymph node metastasis." (PMID 37951919, 2023). "A total of 38 out of 70 cases presented with lymph node metastases, out of which 34 cases showed strong and moderate scores for the overexpression of cyclin D1." (PMID 37007344, 2023). "Studies have shown that the overall amplification of CCND1 is related to lymph node metastasis and invasive tumor histology." (PMID 37644520, 2023). "Of the 123 cases with available lymph node metastases, 11 (9%) had high mean CCND1 CN in their primary tumours, and all but one also had high mean CN in the corresponding lymph node metastasis." (PMID 35459982, 2022). "The strongest predictors of poor survival were high Trop-2 expression (p = 0.03), high cyclin D1 expression (p = 0.04), and lymph node metastasis (p = 0.06)." (PMID 36497418, 2022). "High mean CCND1 CN (mean ≥ 6) in the primary tumour was most often also followed by a concurrent CN increase in the corresponding lymph node metastasis." (PMID 35459982, 2022). "Of these five evaluated parameters, we found that extra thyroidal extension, intraglandular metastasis, and lymph node metastasis were significant predictors of cyclin D1 immunostaining (all P < 0.0001)." (PMID 30885146, 2019). "Several studies have reported the correlation between cyclin D1 overexpression and CCND1 amplification, lymph node metastasis, local recurrence, advanced histological grade (G2/G3), and poor survival." (PMID 29785357, 2018). "Pooled results of those show that both amplification of CCND1 and protein overexpression of cyclin D1 significantly correlate with lymph node metastasis (LNM) in OSCC." (PMID 25663615, 2015).